ENSG00000302122 (novel transcript, antisense to GRIN2A and RP11-89D3.2)
Gene: Long non-coding RNA gene on chromosome 16 (10,181,492 to 10,222,491, forward strand). Ensembl gene ENSG00000302122.
Gene Ontology:
Biological process: SRP-dependent cotranslational protein targeting to membrane, signal sequence recognition
Cellular component: signal recognition particle, endoplasmic reticulum targeting